MGMT (O-6-methylguanine-DNA methyltransferase)
Diseases named in the same sentence as MGMT in open-access papers (continued):
Sharing a sentence is not in itself a finding about the gene and the disease.
glioma (continued). "Finally, we found that miR-340 expression did not correlate with different glioma tumor stages and with MGMT methylation status." (PMID 26799668, 2016). "An expression of MGMT in tumour cells may determine response to TMZ and silencing of MGMT gene by promoter methylation plays an important role in regulation of MGMT activity in gliomas." (PMID 26309255, 2015). "Glioma cells might be sensitized to the alkylating agent temozolomide (TMZ), and combined therapy of IFN-β and TMZ resulted in a favorable outcome in patients with tumors with O6-methylguanine DNA methyltransferase (MGMT) promotor methylation." (PMID 26441059, 2015). "Besides MGMT, hypermethylation at the promoter of several tumor suppressors, apoptotic, or Wnt-signaling pathway involved genes and hypomethylation of normally silenced genes such as CD133, MMP9, or IL8 have also been identified among the glioma patients." (PMID 26451167, 2015). "Several miRNAs have been correlated with glioma progression and prognosis; however, despite the reported link between miRNA expression and the prognosis of GBM specifically, there have been no studies exploring the prognostic role of miRNAs with respect to MGMT promoter methylation status." (PMID 26320189, 2015). "Furthermore, irrespective of the MGMT methylation status, the prognosis of glioma patients can be improved if total resection is performed." (PMID 24160898, 2013). "MGMT mRNA expression varies among different types of gliomas, lacking in approximately 30% of them." (PMID 22852080, 2012). "In the multivariate Cox regression, we found high-expression of BSP, no MGMT methylation, low KPS were independent risk factors of poor prognosis (both OS and PFS) in grade IV glioma patients, while lack of radiotherapy only related to shorter OS but not affect PFS." (PMID 23119009, 2012). "Despite this variety of available techniques, a generally accepted consensus as to the most suitable method of assessing MGMT promoter methylation in glioma tissues has not been achieved so far, neither for the requirements of large clinical trials nor for routine diagnostics." (PMID 22428052, 2012). "The expression of O6-methylguanine-DNA methyltransferase (MGMT) abolished all these effects, indicating that O6-alkylguanine induced by these drugs is the primary lesion responsible for the formation of DSBs and increased sensitivity of glioma cells following knockdown of Rad51 and BRCA2." (PMID 22073281, 2011). "Previous work has also considered how molecular markers may be used in clinical decision-making for recurrent surgery for high-grade gliomas particularly for unmethylated MGMT promoter and wildtype IDH1 gliomas—since no other treatment option has demonstrated a survival benefit for these subgroups." (PMID 39767640, 2024).
glioma (continued). "Fifthly, gliomas with unmethylated MGMT promoter seemed to correspond to an increased level of ANG in contrast to their methylated counterparts, though statistical significance was not reached in CGGA301, which might be due to a high number of missing value on MGMT status." (PMID 37928479, 2023). "Thus, sufficient silencing of the MGMT gene may not occur in these IDHmt gliomas, leading to MGMT expression, followed by remnant capacity for DNA repair." (PMID 36831683, 2023). "Of note, it remains unknown whether there is a difference in therapy-induced senescence across glioma subtypes, such as astrocytoma versus oligodendroglioma, low-grade versus high-grade, and across molecular characteristics (IDH-wild type versus mutant, MGMT methylated versus unmethylated)." (PMID 38030881, 2023). "This phenomenon rarely occurs in newly diagnosed gliomas, but it is common in recurrent tumors after the use of alkylating agents This may partially explain the resistance observed in recurrent tumors regardless of the methylation status of the MGMT promoter." (PMID 36009577, 2022). "Importantly, we show that five specific myeloid cell subtype gene signatures (MC2–MC5, and MC7) are independent prognostic indicators of glioma patient survival, independent of known covariates of glioma patient survival, such as IDH mutation and MGMT methylation status." (PMID 35140215, 2022). "It is now also being realized that promoter methylation is not the only factor driving MGMT expression, but MGMT genomic rearrangements also have a fair share in determining MGMT expression with the evidence of such MGMT genomic rearrangements in recurrent gliomas leading to MGMT overexpression." (PMID 35682901, 2022). "In addition, the lack of other important glioma molecular markers, such as MGMT promoter methylation status and 1p19q co-deletion status, may also affect the construction of the nomogram." (PMID 34964788, 2021). "Past studies have suggested that MGMT may serve as a transcriptional target of GLI1 by virtue of GLI-binding sites within its promoter region; however, it was only until recently that evidence has shown that aberrant GLI1 activation regulates MGMT expression to confer chemoresistance in glioma." (PMID 34638233, 2021). "Importantly, the inhibitory role of TMZ–POH in MGMT is a universal phenomenon observed in all detected cell lines, independent of the cell types, thus explaining the reason why TMZ–POH exerts its anti-tumor activity in cells with MGMT high expression even in TMZ-resistant gliomas." (PMID 29426908, 2018). "The aim of this study was to analyze whether genetic changes of MGMT, IDH1/2 and BRAF occur in PXA or gcGBM and if these genetic changes, respectively their distinct distribution pattern, could be used as molecular markers in the differentiation of these glial tumor entities." (PMID 27253461, 2016). "Although MGMT mRNA might not always represent MGMT protein expression, MGMT transcript has been tested in few studies in relation to glioma, mainly by quantitative reverse-transcription polymerase chain reaction (RT-qPCR) and less frequently by in situ hybridization." (PMID 26035292, 2015). "Interestingly, MGMT was found hypermethylated in all long-term survivors (LTS) GBM patients, defined as those patients with a median survival time of more than 3 years, proving the study of this gene as a clinically relevant predictor of response to treatment in glioma patients." (PMID 22852080, 2012).
glioma (continued). "It is predominantly found in Grade 4 gliomas, particularly those that are IDH‐wildtype, 1p/19q noncodeleted, mesenchymal subtype, and MGMT unmethylated." (PMID 40090864, 2025). "Critical indicators of poor prognosis in gliomas include IDH (Isocitrate Dehydrogenase) (NADP[+]) wild‐type status, absence of 1p/19q codeletion, and an unmethylated MGMT promoter." (PMID 40090864, 2025). "We next tested the three-dimensional growth of T98 and LN18 glioma cells, which are additional high MGMT-expressing GBM cell lines transfected with anti-MGMT siRNA or non-targeting siRNA." (PMID 40336841, 2025). "Therefore, given that the MGMT promoter methylation level can be used to predict the curative effects of TMZ, combining chemotherapy with drugs that target methylation changes may represent a promising new therapeutic approach for treating gliomas in the future." (PMID 40469294, 2025). "The study focused on glioma subtyping according to the IDH genotype and the 1p/19q codeletion status, but it did not consider other molecular biomarkers, such as o6-methylguanine DNA methyltransferase (MGMT)." (PMID 40075780, 2025). "In samples without 1p/19q co-deletion, without MGMT promoter methylation, and in IDH wild-type glioma patients, we also found that patients had higher SIGLEC7 levels compared to the control group." (PMID 39211050, 2024). "According to the 2017 Guidelines for Central nervous System Tumors in the United States, TT-Fields can be used in GBM with KPS≥60 and MGMT promoter methylation or non-methylation." (PMID 38835394, 2024). "Given that MGMT resides on chromosome 10, it has been reported that compared to GBM, where at least one copy of chromosome 10 is lost, IDHmt lower-grade gliomas do not lose either copy." (PMID 36831683, 2023). "Advanced age, higher grade, MGMT non-methylation, and IDH wild type are all poor prognostic factors in glioma patients." (PMID 36959804, 2023). "MGMT promoter methylation does not occur in non-neoplastic cells, meaning they can upregulate MGMT gene expression and be less sensitive to TMZ than glioma cells with MGMT promoter methylation." (PMID 37919784, 2023). "High expression of CDC42 in glioma patients was positively correlated with poor prognostic factors (higher WHO grade, IDH wild-type, MGMT non-methylated status, and 1p19q non-codeletion status)." (PMID 37476838, 2023). "This functional discordance of CELF2 is exemplified by its good prognostic value in low-grade gliomas, whereas it is of poor prognosis in classical GBM subtypes not methylated on the MGMT promoter." (PMID 37894405, 2023). "Taking all into account, including the systematic evidence that MGMT activity abrogates TMZ toxicity, repair of N7mG and N3mA does not seem to influence TMZ toxicity in gliomas to great extent; this is probably due to multiple coping repair mechanisms." (PMID 35626024, 2022). "High angiogenesis pathway score gliomas demonstrated a predilection for aggressive clinicopathological characteristics, such as higher grade, IDH wildtype genotype, 1p19q non-codeletion, MGMT promoter unmethylated status, and mesenchymal subtype." (PMID 35579998, 2022). "Furthermore, we explored the correlation between SQLE expression and clinicopathological features in glioma, the results showed that SQLE expression was significantly associated with WHO grade and 1p/19q co‐deletion, and was not related to age, gender, IDH status, and MGMT methylation status." (PMID 35962621, 2022).
glioma (continued). "High HOXA5 expression samples contain unfavorable clinical features of glioma, including IDH wild type, un-methylated MGMT status, non-codeletion 1p19q status, malignant molecular subtype." (PMID 34485110, 2021). "A significant association with OS was demonstrated for patients’ performance status, whereas the extent of surgery, age, MGMT promoter status, and IDH status did not predict patients’ OS in glioma recurrence." (PMID 34671551, 2021). "18F-FET PET outcome for GR (positive/negative) was not significantly different considering the glioma IDH status (p-value: 0.894) and MGMT methylation status (p-value: 0.996)." (PMID 34671551, 2021). "Surprisingly, our analysis showed that the prognostic value of MGMT promotor methylation was only retained in patients with astrocytoma, IDH wild-type, but not in IDH mutant glioma with or without 1p19q co-deletion." (PMID 33184319, 2020). "In this respect, we identify four lncRNAs with prognostic value in glioma patients that are involved in the transcriptional response to TMZ, independent of MGMT status." (PMID 32927769, 2020). "The results revealed that the expression of MLK3 mRNA in human gliomas was correlated with IDH status but not 1p/19q codeletion and MGMT promoter methylation status." (PMID 33692940, 2020). "GLRX was found to be highly enriched in gliomas of higher grades with wild-type IDH, without 1p/19q co-deletion, and with a methylated MGMT promoter." (PMID 33329553, 2020). "Recruitment into clinical trials is largely based on a histological diagnosis of glioma, with or without specific genetic markers such as isocitrate dehydrogenase (IDH) and O6-methylguanine-DNA methyltransferase (MGMT) gene methylation." (PMID 30008798, 2018). "MGMT promoter methylation and consequently low MGMT expression is typical in, but not unique to IDH1 mutant gliomas, which generally respond better to TMZ than their IDH1 wild type (WT) counterparts." (PMID 28178660, 2017). "In regards to clinical features of gliomas, V-ATPase G1 was more expressed by tumors wild-type for IDH1 enzyme whereas it did not correlate to MGMT promoter methylation." (PMID 26020805, 2015). "This pattern of large CNAs in IDHwt gliomas contrasts with IDHmut gliomas, in which changes on chromosomes 7 and 10 were either absent or more focal around the EGFR, MGMT, and/or PTEN genes (Arrows)." (PMID 26091668, 2015). "Together the data implies that APE1, NBN, PMS2, MGMT and PTEN do not influence paediatric glioma pathogenesis." (PMID 25026297, 2014). "Furthermore, we discovered that Valproic acid, one of histone deacetylase inhibitors, suppressed growth of the transformed astrocyte cells without increasing MGMT protein, suggesting that such epigenetic compounds may be used to some types of gliomas in combination with alkylating agents." (PMID 17547775, 2007). "Importantly, the methylation status of MGMT in gliomas at presentation does not correlate with the clinical response when temozolamide is used at relapse, demonstrating that the value of biomarkers may depend on when during tumour progression or treatment they are measured." (PMID 16495912, 2006). "Furthermore, the expression increased with the grade of glioma and is correlated with IDH wildtype, MGMT unmethylated status, and 1p19q non-codeletion." (PMID 38519889, 2024). "Notably, SIRT5 was downregulated in recurrent and secondary gliomas, as well as gliomas with specific genetic characteristics, such as the IDH wildtype, unmethylated MGMT, and 1p19q non-codeletion." (PMID 39201811, 2024).
glioma (continued). "At present, the first-line treatment drug temozolomide (TMZ) can effectively improve glioma and astrocytoma with low expression of DNA repair enzyme O6-methylguanine-DNA-methyltransferase (MGMT), while the clinical treatment for glioma with high MGMT expression is still lacking." (PMID 39548081, 2024). "Irrespective of the methylation status of the MGMT promoter, elevated levels of FAP were observed in gliomas of all grades, regardless of whether they were methylated or unmethylated." (PMID 37864148, 2023). "Although hereditary DNA repair defects (involving the BRCA genes) have not been described to play a role in gliomas, downregulation or pharmacologic inhibition of HR or PARP-1 may be a reasonable strategy, notably for MGMT-expressing tumors." (PMID 38068493, 2023). "Recent literature has taken into account the existence of different prognostic factors (i.e., age, MGMT methylation status, EOR, preoperative PS) that may variably influence OS in gliomas, regardless of their location." (PMID 36672311, 2023). "Furthermore, for recurrent gliomas, standard-of-care treatments are not well defined; treatment is usually selected based on prior therapy, age, Karnofsky Performance Scale (KPS), MGMT promoter methylation status, and patterns of disease progression." (PMID 35222252, 2022). "Analysis of the TCGA database and the CGGA_325, CGGA_693 datasets showed significantly higher ALKBH5 mRNA levels in the glioma patients with wild-type IDH and chromosomal 1p/19q non-codeletion, and significantly reduced in the glioma patients with MGMT promoter methylation." (PMID 35444654, 2022). "On the other hand, the high proportion of CAF is mainly enriched in glioma patients with higher age (P < 0.0001), high WHO grade (P < 0.001), IDH wildtype status (P < 0.001), 1p/19q non-codeletion status (P < 0.001), and MGMT promoter un-methylated status (P < 0.01)." (PMID 34778248, 2021). "In our study, we identified a unique subtype of gliomas based on the expression of ARLs, in which cluster 1 was associated with poor prognosis and enriched with the malignant subtype of gliomas including IDH1 wildtype, 1p19q non-codeleted, and MGMT unmethylated ones." (PMID 34211979, 2021). "Similarly, none of the three tested canine glial tumour cell lines (J3T‐BG, SDT3G and G06A) had detectable MGMT levels in comparison to recombinant MGMT control and A549 cell lysate." (PMID 34477324, 2021). "Finally, another study found no influence of 10q LOH over OS independently of MGMT methylation status, but it was performed on a cohort of mix GBM and low grade gliomas." (PMID 32666673, 2020). "However, in our results, MGMT and MMP-9 did not increase in patients with nonlocal recurrence; we infer that these two mechanisms are not related to the nonlocal recurrence of glioma." (PMID 33585189, 2020). "Moreover, we also found that GLRX expression was significantly higher in glioma patients with malignant molecular phenotypes, including those harboring the IDH wild-type state, 1p/19q non-codeletion state, and MGMT unmethylated promoters." (PMID 33329553, 2020). "In addition, in grade 2 glioma patients, we also observed that the ELR was higher in tumors with MGMT promoter methylation than in those without methylation." (PMID 31805879, 2019). "The results showed the molecular pathology factors, except for MGMT, could impact the ELR in grade 2 glioma (P = 0.04), but none influenced Eo and ELR." (PMID 31805879, 2019). "However, there was no consistent relationship between MGMT proteins level and IDH-1R132H status within any of the individual glioma subtypes." (PMID 27120786, 2016).